OR4S1 (olfactory receptor family 4 subfamily S member 1)
Description:
Odorant receptor.
Synonyms: OR11-100
Tractability: Antibody: UniProt places it where antibodies can reach, with medium confidence; UniProt predicts a signal peptide or a membrane-spanning region; its Gene Ontology location is reachable by antibodies, with medium confidence.
Gene: Protein-coding gene on chromosome 11 (48,306,223 to 48,307,152, forward strand). Ensembl gene ENSG00000176555.
Subcellular location: Cell membrane
Pathways (Reactome):
Sensory Perception: Expression and translocation of olfactory receptors
Gene Ontology:
Molecular function: olfactory receptor activity; G protein-coupled receptor activity
Biological process: detection of chemical stimulus involved in sensory perception of smell; G protein-coupled receptor signaling pathway
Cellular component: plasma membrane; membrane
Genetic constraint (gnomAD): Loss-of-function variants: 1 observed, 0.52 expected, observed/expected ratio (o/e) 1.92, 90% interval 0.34 to 1.93. That is too few expected variants to judge how well the gene tolerates losing a copy. Missense variants: 531 observed, 402.4 expected, observed/expected ratio (o/e) 1.32, 90% interval 1.23 to 1.42. Synonymous variants: 197 observed, 153.19 expected, observed/expected ratio (o/e) 1.29, 90% interval 1.14 to 1.45.
Homologues: Orthologues: chimpanzee OR4S1 (97% identical). Paralogues in human: OR4S2 (59% identical), OR4X1 (55% identical), OR4C3 (54% identical), OR4B1 (53% identical), OR4C15 (53% identical), OR4C12 (52% identical), OR4C46 (52% identical), OR4A15 (52% identical), OR4P4 (51% identical), OR4C13 (51% identical), OR4C6 (51% identical), OR4C11 (51% identical), and 116 more.
Diseases named in the same sentence as OR4S1 in open-access papers:
OR4S1 is named in the same sentence as 1 disease in open-access papers, as found by Europe PMC text mining. Sharing a sentence is not in itself a finding about the gene and the disease.
OR4S1 shares sentences with these, for which no sentence is quoted: cardiac disease (1 paper).